FGF21 (fibroblast growth factor 21)
Diseases named in the same sentence as FGF21 in open-access papers (continued):
Sharing a sentence is not in itself a finding about the gene and the disease.
mitochondrial disease (continued). "Amongst patients with genetically confirmed mitochondrial disease (group 1) we found 3 who had normal levels of FGF-21 but elevated GDF-15 and they all had the common MELAS mutation." (PMID 26867126, 2016). "Serum FGF21 levels are significantly increased in human mitochondrial disease and the best predictor of mitochondrial disease among classical indicators including creatine kinase, lactate, and ­pyruvate." (PMID 26483756, 2015). "In contrast, FGF-21 (fibroblast growth factor 21) has recently been proposed as a valuable serum measure in inherited mitochondrial disease." (PMID 24252301, 2013). "There is an association between increasing concentrations of FGF-21 with mitochondrial diseases, suggesting FGF-21 as a biomarker for diagnosis of primary MIDs in humans." (PMID 24078096, 2013). "FGF-21 concentrations in serum seemed to increase with increasing clinical severity of the mitochondrial disease and muscle pathology." (PMID 24078096, 2013). "Firstly, the prior study demonstrating serum FGF-21 elevation in mitochondrial disease included a large number of patients with childhood-onset disease." (PMID 24252301, 2013). "Serum fibroblast growth factor-21 (FGF-21) is a new specific marker for mitochondrial disease and might facilitate diagnosis." (PMID 38784375, 2024). "In the Abcb10 cKO mice, the gene expression of the mitochondrial disease biomarkers Gdf15 (growth differentiated factor 15) and Fgf21(fibroblast growth factor 21) gradually increased with age, suggesting that mitochondrial dysfunction became progressively more severe as these mice aged." (PMID 38655715, 2024). "Yet, this observation agrees with FGF21 being related to muscular system presentation, while GDF15 may be linked to more generalized mitochondrial disease and indicative of disease severity and/or progression." (PMID 34972147, 2021). "Growth differentiation factor 15 (GDF15) and fibroblast growth factor 21 (FGF21) are representative metabokines that are responsive to mitochondrial diseases, and their expression is stimulated through ATF4, CHOP, and XBP1, key components of the integrated stress response." (PMID 33718833, 2021). "In combination with FGF-21 and GDF-15, NF-L, and potentially cell-free mtDNA, may contribute to narrowing the choice of diagnostic test in cases of suspected mitochondrial disease." (PMID 33501425, 2021). "However, prospective multi-centre studies will be necessary to confirm the role of NF-L as a biomarker, and how it, together with GDF-15 and FGF-21, can be used most profitably in the investigation of mitochondrial disease." (PMID 33501425, 2021). "However, this was accompanied by an increase in serum biomarkers of mitochondrial disease, including fibroblast growth factor 21 (FGF‐21), growth and differentiation factor 15 (GDF‐15), plus dysregulation of fatty acid and amino acid metabolism." (PMID 32107855, 2020). "Besides the traditional marker of OXPHOS dysfunction, the pathological increase of lactic acid, promising biomarkers for mitochondrial disease have been recently proposed, including fibroblast growth factor 21 (FGF21), GDF-15, and creatine." (PMID 32851462, 2020). "FGF-21 was first introduced in 2011 as a biomarker for the diagnosis of mitochondrial diseases." (PMID 30897730, 2019). "It has been suggested that the increase in FGF-21 concentrations in serum might occur with increasing clinical severity, progression of mitochondrial disease, and muscle pathology." (PMID 30897730, 2019). "Serum fibroblast growth factor 21 (FGF-21) is a biomarker for mitochondrial disease and could be a candidate to monitor mitochondrial function in the deleterious course of disease." (PMID 30159853, 2018). "Nevertheless, according to our findings, testing patients suspected of a mitochondrial diseases, for organic acids in urine and FGF21 in plasma is informative and the results facilitate the decision whether to perform a biopsy or not." (PMID 28287425, 2017).
mitochondrial disease (continued). "In the past 5 years, serum fibroblast growth factor-21 (FGF-21) and serum growth and differentiation factor-15 (GDF-15) have emerged as two promising diagnostic biomarkers for mitochondrial diseases." (PMID 28969370, 2017). "In the light of previous data showing that FGF-21 may be useful in a subgroup of patients with mitochondrial disease, in 2013 we adopted measurement of FGF-21 as an adjunct to first-line routine laboratory tests." (PMID 28825656, 2017). "Interestingly, a combined evaluation of both GDF-15 and FGF-21 in serum from adult patients with mitochondrial disease did not improve the diagnostic value of the individual tests." (PMID 38515869, 2024). "Finally, we reported a positive correlation between mtDNA-CN and FGF21 expression levels in liver tissue samples of patients with NAFLD which might be a mitochondrial disease." (PMID 37347041, 2023). "In addition, FGF21 is also defined as highly predictive biomarker for mitochondrial diseases." (PMID 35004861, 2021). "Therefore, serum FGF21 was reported as a potential biomarker for mitochondrial diseases." (PMID 32397676, 2020). "Furthermore, FGF-21 specificity for mitochondrial disease has been determined to be above 90%." (PMID 30406383, 2018). "Mitochondrial stress also influences FGF‐21 and GDF‐15 production, both biomarkers of mitochondrial diseases." (PMID 41496770, 2025). "FGF21 and GDF15 are well-known mitochondrial biomarkers that showed remarkable elevations in mitochondrial diseases, respectively." (PMID 39124668, 2024). "Changes in serum levels of Fibroblast-growth-factor 21 (FGF-21) and Growth-differentiation-factor 15 (GDF-15) are characteristic of some metabolic and mitochondrial diseases." (PMID 36935492, 2023). "With regard to the diagnosis of mitochondrial diseases, GDF-15 seems to have an improved sensitivity and specificity in comparison to FGF-21." (PMID 34572118, 2021). "Two new biomarkers, fibroblast growth factor 21 (FGF-21) and growth and differentiation factor 15 (GDF-15), have been described for mitochondrial disease." (PMID 33501425, 2021). "We also confirmed that FGF-21 and GDF-15 are useful biomarkers for mitochondrial disease in which myopathy is the major or only manifestation." (PMID 33501425, 2021). "On the other hand, they also observed increased serum levels of fibroblast growth factor 21 (FGF-21), growth and differentiation factor 15 (GDF-15) both proposed as biomarkers of mitochondrial disease." (PMID 34199142, 2021). "FGF-21 and GDF-15 are both primarily elevated in mitochondrial disease affecting muscle although GDF-15 appears more sensitive in detecting mitochondrial dysfunction affecting other organs." (PMID 33501425, 2021). "Our data indicate that GDF-15 is a valuable serum quantitative biomarker for the diagnosis of mitochondrial diseases in children and that measurement of both GDF-15 and FGF-21 improves the disease detection ability of either factor separately." (PMID 26867126, 2016). "Also, the expression of the circulating cytokines fibroblast growth factor 21 (FGF21) and growth/differentiation factor 15 (GDF15), found upregulated in various mitochondrial disease models, was significantly induced in PolɣD1135A cells." (PMID 39918244, 2025). "Importantly, numerous studies have demonstrated elevated levels of serum FGF21 and GDF15 in patients with mitochondrial disease (MD) characterized by myopathy, but also in age-related diseases." (PMID 37941910, 2023). "In our cross-sectional analysis of CPHIV who did or did not meet clinical definitions of “possible” mitochondrial disease, we found significantly higher plasma levels of the mitokines FGF21 and/or GDF15 in those with MDC score ≥3." (PMID 34972147, 2021). "On the other hand, GDF15 seems to be more indicative of mitochondrial diseases regardless of clinical phenotype, whereas FGF21 sensitivity for mitochondrial diseases is higher when muscle manifestations are present." (PMID 32397676, 2020).
mitochondrial disease (continued). "Likewise serum FGF21, serum GDF15 seems to be a more specific marker for mitochondrial diseases due to mitochondrial translation and mtDNA maintenance defects, as opposed to those resulting from impaired respiratory chain complex or assembly factors." (PMID 32397676, 2020). "Similarly to FGF21, the reliability and efficacy of GDF15 as a biomarker of mitochondrial diseases remains to be tested in others patient cohorts." (PMID 32397676, 2020). "Although skeletal muscle is not considered to be a source or target of FGF21, a recent report indicated that FGF21 expression is enhanced in muscle from HIV patients, a phenomenon also reported in other conditions of skeletal muscle stress such as mitochondrial diseases." (PMID 29661866, 2018). "Novel biomarkers, like fibroblast growth factor 21 (FGF-21) which has been shown to be a sensitive and specific biomarker for mitochondrial disease affecting skeletal muscles, may play a more crucial role in the future." (PMID 28587136, 2017). "We found mRNA expression of Fgf21 and Gdf15, which are markers of mitochondrial disease, but could not show any improvement with NMN administration." (PMID 37793777, 2023). "Interestingly, the combined assessment of the serum levels of both FGF-21 and GDF-15 from adult patients with mitochondrial disease has not been found to improve the diagnostic value of the individual tests." (PMID 35806492, 2022). "Additionally, this suggests that FGF21 and GDF15, which are biomarkers of mitochondrial diseases, could be used to follow treatment responses and disease progression/recovery in patients with mitochondrial disease." (PMID 33128823, 2020). "The study used a healthy group of children without mitochondrial disease and compared them to those with MRC; results suggested that FGF21 outperforms GDF15 when discriminating between both groups." (PMID 35806492, 2022).
tumor (68 papers, 2013 to 2026). "Tumour-secreted FGF21 has shown immune-checkpoint factor functions, and high FGF21 levels are associated with a poor prognosis for patients." (PMID 40242310, 2025). "Our initial findings revealed reduced FGF21 expression in PDAC tissues, which correlated with advanced tumor stage, lymph node metastasis, vascular invasion, and poor prognosis, implicating FGF21 loss in PDAC aggressiveness." (PMID 41426308, 2025). "Although previous studies have suggested that FGF21 levels are a promising predictive biomarker for tumor progression, no previous study has identified the mechanism underlying the effects of FGF21 on tumor progression in extrahepatic tissues." (PMID 31408968, 2019). "Given that this study focussed on unresectable HCC, we speculate that the increased FGF21 levels are primarily attributed to tumour secretion, with only limited association with a compromised hepatic reserve." (PMID 40242310, 2025). "Similarly, in urothelial carcinoma, serum FGF21 level was positively associated with the tumor stage, cardiovascular disease, and history of recurrence." (PMID 36263162, 2022). "These limited data suggest the great suitability of serum FGF21 as a diagnostic biomarker of cancers, and also open the door for the speculation that an FGF21-driven liver-adipose tissue-tumor tissue axis is implicated in cancers." (PMID 36263162, 2022). "We suggest that the tumor-delaying effect of FGFR4 deficiency may be in large part due to elevated anti-obesogenic FGF21 that triggers tumor-suppressing signals from both peripheral and breast adipocytes." (PMID 24279986, 2013). "Another substrate, FGF21, is a key factor in metabolic regulation, and in response to various metabolic and cellular stresses, it is significantly upregulated to reduce excessive lipids and glucose and ameliorate tissue damage caused by metaflammation, which is a risk factor for tumor growth." (PMID 34068501, 2021). "The heightened macrophage infiltration and collagen deposition observed in FGF21-low tumors indicate a more pronounced inflammatory response within the tumor microenvironment." (PMID 41426308, 2025). "It showed that a negative correlation exists between TNM stages and FGF21 expression levels, where lower FGF21 expression in PDAC predicts higher tumor stages." (PMID 41426308, 2025). "In PCa, FGF21 has been shown to function as a tumor suppressor by accelerating autophagy while reducing proliferation and metastasis." (PMID 40740483, 2025). "Tumor-secreted FGF21 maintains the hyperactivation of the AKT-mTORC1-SREBP1 signaling axis in activated CD8+ T cells, leading to cholesterol biosynthesis and T cell exhaustion." (PMID 41245411, 2025). "When secreted by tumours, FGF21 significantly disrupts the anti-cancer ability of the immune system by altering cholesterol metabolism within CD8+ T cells." (PMID 40242310, 2025). "Consistent with this, we observed a higher intratumoral density of FGF21 in the FGF21 treatment group, which corresponded with faster tumor growth and higher tumor weight." (PMID 38238320, 2024). "We used the chemotherapy drug doxorubicin (DOX) as an apoptosis inducer and observed antagonistic interactions between DOX and FGF21 on tumor cell viability." (PMID 38238320, 2024). "To further investigate the role of FGF21 in NAFLD-induced tumor growth, we used FGF21 knockout mice." (PMID 38238320, 2024). "A similar trend was observed in PyVT mice, although the enrichment of FGF21 was more apparent in the peritumoral areas, with both adipose tissue and the core tumor area showing low expression of FGF21." (PMID 38238320, 2024). "Mechanistically, FGF21 is involved in multiple processes of tumor progression through specific signaling pathways that depend on the type of cancer and the source of FGF21." (PMID 38238320, 2024).
tumor (continued). "Additionally, FGF21 may be inactivated by cleavage by Fibroblast Activation Protein (FAP), affecting GBM cell metabolic regulation and tumor progression, This aligns with our findings that FGF21 may mediate the causal relationship between PC16 and GBM as an intermediary factor." (PMID 39286013, 2024). "Immunohistochemistry (IHC) staining of tumor samples collected after 2 h of FGF21 administration confirmed the in-situ enrichment of FGF21." (PMID 38238320, 2024). "In our study, we observed FGF21 aggregation in tumors from the HFD and FGF21 administration groups, suggesting a positive correlation between FGF21 expression and tumor development." (PMID 38238320, 2024). "Consistent with the tumor-promoting effects observed in mice and cell lines, patients with high expression levels of FGF21 showed significantly shorter overall survival time and shorter disease-free survival." (PMID 38238320, 2024). "The content of FGF21 in PTC patients is comparatively high, and FGF21 can promote tumor deterioration by activating the FGFR signal axis to upregulate EMT signal transduction." (PMID 37345200, 2023). "Chronic cold-induced fibroblast growth factor 21 (FGF21) and fatty acid metabolism can trigger tumor growth, whereas competition for glucose represses tumor development." (PMID 36980222, 2023). "p38, STAT3, ERK1/2, and JNK phosphorylation were generally higher in ATF4-deficient tumours, which expressed more EREG but less FGF21 mRNA." (PMID 36996941, 2023). "We have shown that the FGF-2/FGF-21 MN patch has good therapeutic effects in alleviating UVB-induced skin photoaging by reducing inflammation and promoting collagen synthesis both in vitro and in vivo." (PMID 37426882, 2023). "On the other hand, some studies have discussed the tumor suppressor effects of FGF21 on HCC under both physiological and pharmacological levels." (PMID 36263162, 2022). "In vitro study showed that FGF21 was elevated in tumor cells compared with normal lung cell lines, which facilitated tumor progression by promoting cell growth, migration, and defending oxidative stress via Sirtuin 1/PI3K/AKT signaling." (PMID 36263162, 2022). "In this setting, recruiting FGF21 from either adjacent or distant organs will benefit tumor tissues against adverse environments." (PMID 36263162, 2022). "In vitro FGF21 treatment promoted tumor cell migration and invasion by upregulating FGFR-EMT signaling." (PMID 36263162, 2022). "So far, there is limited information available to explain the role of FGF21 in tumor initiation and progression." (PMID 36263162, 2022). "Higher FGF21 expression was correlated with more resistance to sorafenib treatment in HCC patients, and intra-tumoral FGF21 knockdown effectively inhibited tumor growth in sorafenib-resistant HCC animal models." (PMID 36263162, 2022). "For the carcinogen-induced HCC animal model, increased FGF21 levels were observed in the early and middle stages of tumorigenesis, and also in normal hepatocytes adjacent to the tumor foci, while sharply diminished once cells progressed to malignancy." (PMID 36263162, 2022). "Thus, it could be worthwhile to study the effect of autocrine FGF21 induced by autophagy-deficient hepatocytes on the tumor arising from autophagy-deficient hepatocytes, which could be of clinical value for understanding the behavior of autophagy-deficient cancer and its management." (PMID 35321438, 2022). "Taken together, the results showed that FGF21 concentrations were higher in poorly and moderately differentiated tumours compared with highly differentiated tumours." (PMID 36578551, 2022). "It has been demonstrated that high serum levels of FGF21 in PTC patients were significantly related to an aggressive tumor phenotype and poor prognosis." (PMID 36077709, 2022). "The mitochondrial dysfunction and retrograde mitochondrial signaling evidentially produced overexpression of fibroblast growth factor 21 (fgf21) and growth differentiation factor 15 (gdf15) in tumor patients." (PMID 34717757, 2021).